INS (insulin)
Diseases named in the same sentence as INS in open-access papers (continued):
Sharing a sentence is not in itself a finding about the gene and the disease.
β-cell deficiency (6 papers, 2014 to 2025). "All were diagnosed with neonatal diabetes and required full insulin replacement, consistent with complete β cell deficiency." (PMID 40924476, 2025). "It is calculated using the steady-state fasting glucose and insulin concentrations to concomitantly estimate the degrees of β-cell deficiency and the target-tissue sensitivity to insulin." (PMID 24524730, 2014). "Because insulin from β cells functions to reduce levels of circulating glucose, we tested whether the β cell deficiency in GF larvae at 6 dpf affected the metabolic function of the fish by measuring free glucose levels." (PMID 27960075, 2016).
abdominal aortic aneurysm (5 papers, 2017 to 2023). Enlargement and ballooning of the vessel that supplies arterial blood to the abdomen, pelvis and legs. "Changes in p-glucose, s-insulin, and p-glucagon between nadir and 2-hours sample after oral glucose tolerance testing in 65-year-old men with and without abdominal aortic aneurysm (AAA) at ultrasound screening." (PMID 37731907, 2023).
age-related macular degeneration (5 papers, 2021 to 2025). Age-related loss of vision in the central portion of the retina (macula), secondary to retinal degeneration. "Insulin provides trophic signals that counteract photoreceptor degeneration, a key event in RP, age-related macular degeneration, and DR." (PMID 41301488, 2025). "Disruption of insulin signaling in these cells can lead to impaired glucose metabolism, increased oxidative stress, and accelerated photoreceptor degeneration, as observed in models of DR, RP, and age-related macular degeneration." (PMID 41301488, 2025). "The aberrantly presented pHc in liver cells, pancreatic cells, and RPE cells might be relevant to insulin resistance, insulin processing deficits, and age-related macular degeneration (AMD), pathologies frequently related to T2DM." (PMID 40885383, 2025).
Alkalosis (5 papers, 2018 to 2024). Depletion of acid or accumulation base in the body fluids. "It has been known that the transcellular shifting of potassium is initiated by the thyroid hormone, catecholamine, excessive aldosterone, insulin function or alkalosis." (PMID 37061666, 2023).
anaphylaxis (5 papers, 2018 to 2024). An acute hypersensitivity reaction that occurs from exposure to an allergen. "Insulin allergy affects 0.1–3% of insulin-treated diabetics and causes symptoms ranging from localized itching and rash to life-threatening anaphylaxis." (PMID 30258565, 2018). "She developed progressive and severe immediate hypersensitivity reactions to insulin, including anaphylaxis." (PMID 37228579, 2023). "In case of a history of anaphylaxis in insulin dependent patients, desensitization should always be performed." (PMID 30258565, 2018). "In patients not receiving Neutral Protamine Hagedorn (NPH) insulin and protamine-zinc insulin (PZI), the incidence of hypotensive adverse reactions is reported to be 0.06%, whereas anaphylaxis-like reactions (severe hypotensive reactions) in patients receiving NPH insulin are shown to be 0.6%." (PMID 39303134, 2024).
Anosmia (5 papers, 2013 to 2023). An inability to perceive odors. "Recently, intranasal insulin fast-dissolving films for the treatment of anosmia in patients post-COVID-19 infection were investigated." (PMID 37366867, 2023). "Despite the limited number of patients, this study showed that intranasal insulin (40 IU) administration was able to increase odor identification, suggesting that insulin-dissolving films could be a promising approach to anosmia treatment." (PMID 37366867, 2023). "Likewise, the role of insulin in triggering anosmia has formerly been suggested." (PMID 36012880, 2022).
Central hypothyroidism (5 papers, 2016 to 2025). A type of hypothyroidism due to an insufficient stimulation of an otherwise normal thyroid gland. "All patients with primary or central hypothyroidism were receiving levothyroxine, those with hypoparathyroidism calcium and calcitriol and the diabetic patients insulin." (PMID 27158435, 2016). "The weakening of hypothalamic insulin and leptin signaling as a result of inactivation of IRS4, which couples the insulin and leptin receptors with PI3K, leads to a decrease in TRH production and central hypothyroidism." (PMID 36834685, 2023).
congenital heart disease (5 papers, 2014 to 2024). A heart disease that is present at birth. "Out of these three, two babies were excluded from the analysis, as the mothers of these babies were diabetic on insulin, which is a high risk factor for congenital heart disease." (PMID 25272289, 2014). "In these studies, maternal obesity was consistently associated with congenital heart disease, several adverse cardiometabolic parameters throughout life including higher body mass index and insulin levels, and greater risk of cardiovascular disease in adulthood." (PMID 35669689, 2022). "There was no statistically significant impact on the occurrence of heart defects in the child of medications containing iodine, heparin, Acard, insulin, or other medications (p > 0.05)." (PMID 39275339, 2024). "Recently, an integrated multi-omics study was performed to characterize the congenital heart and found congenital heart disease (CHD)-specific cell states in cardiomyocytes, which provided evidence of insulin resistance and induced gene expression by FOXO and CRIM1." (PMID 38885281, 2024).
congenital hypothyroidism (5 papers, 2015 to 2023). A thyroid hormone deficiency present from birth. "In summary, patients presenting with mutations in GLIS3 characteristically present with neonatal diabetes with variable insulin sensitivity and congenital hypothyroidism due to a range of underlying causes." (PMID 26259131, 2015). "Since glucose-stimulated Ca2+ fluxes are a major triggering signal for insulin release, we hypothesised that long-term alterations in glucose metabolism induced by congenital hypothyroidism may be linked to changes in beta cell stimulus–secretion coupling." (PMID 32472193, 2020). "It has been observed that congenital hypothyroidism decreased insulin secretion in adulthood, which is related to high glucose concentration." (PMID 31066757, 2019). "Indeed, patients with congenital hypothyroidism were found to have an increased risk of NAFLD and increased fasting glucose and insulin levels." (PMID 37856222, 2023).
diabetic eye disease (5 papers, 2020 to 2025). A group of disorders affecting the eye in patients with diabetes mellitus. "For example, one study demonstrated that transgenic mice overexpressing IGF1R exhibited retinal changes similar to those seen in human diabetic eye disease, including vascular alterations and neovascularization, even under normal glucose and insulin levels." (PMID 40391004, 2025). "The incidence of diabetic eye disease was higher in the insulin pump group across both time periods (p < 0.001)." (PMID 40390300, 2025).
Duchenne muscular dystrophy (5 papers, 2017 to 2025). Duchenne muscular dystrophy (DMD) is a neuromuscular disease characterized by rapidly progressive muscle weakness and wasting due to degeneration of skeletal, smooth and cardiac muscle. "Moreover, the disease Duchenne muscular dystrophy, which is caused by dissociation of the dystrophin glycoprotein complex, is associated with reduced insulin sensitivity in humans." (PMID 35796564, 2022).
emphysema (5 papers, 2006 to 2024). "After conservative treatment including nasal oxygen and adjustment of insulin therapy, follow-up low-dose CT after four days confirmed full regression of the emphysema." (PMID 30997108, 2019).
endometrial tumor (5 papers, 1994 to 2022). "The relationship between tumour growth, insulin status, blood lipids and adipose linoleic acid (LA, reflecting long-term LA intake) was studied in 19 Jewish women suffering from early and advanced stages (ES and AS) of ovarian and endometrial tumours." (PMID 7981074, 1994). "Moreover, previous studies performed in these type of hormone sensible tumors suggest that insulin and insulin-like growth factors (IGFs) could have a role in endometrial tumor genesis." (PMID 34769256, 2021). "Given the important role of insulin and INSR in cancer biology, mainly breast and endometrial tumors, it is expected that future efforts will embrace also the development of INSR-directed molecules." (PMID 36479090, 2022).
Epstein-Barr virus infection (5 papers, 2012 to 2022). An infection that is caused by Epstein-Barr virus. "We also found that BCG vaccination and an unexpected EBV infection in a placebo-treated diabetic subject, both known triggers of innate immunity, caused rapid increases in circulating insulin-autoreactive T cells that were mostly dead." (PMID 22905105, 2012). "As for KEGG analysis, the proteasome, Epstein-Barr virus infection, antigen processing and presentation, insulin signaling pathway, and phagosome were included." (PMID 30755240, 2019). "The TNF-induced death in vivo of insulin-autoreactive T cells with BCG vaccinations or acute EBV infection was confined to the autoreactive T cells." (PMID 22905105, 2012). "The two non-EBV infected placebo-treated subjects’ AUCs were 0.57 and 0.07, while the EBV-infected subject had a strikingly elevated AUC of 5.69, reflecting the large numbers of dead insulin-autoreactive T cells being released into the circulation after the EBV infection." (PMID 22905105, 2012). "The presence of the new EBV infection in blood samples was detected during our blinded laboratory protocols that required analysis of EBV-reactive T cells (EBV-tetramer positive CD8 T cells) as a control during the CD8 insulin-autoreactive T cell assays." (PMID 22905105, 2012). "BCG-treated patients and one placebo-treated patient who, after enrollment, unexpectedly developed acute Epstein-Barr virus infection, a known TNF inducer, exclusively showed increases in dead insulin-autoreactive T cells and induction of Tregs." (PMID 22905105, 2012). "Similar, if not greater elevations in circulating insulin-autoreactive T cells were also seen in the EBV-infected placebo subject coincident with the T cell and serologic immune response to an ongoing EBV infection (Fig. 4Aiii)." (PMID 22905105, 2012).
fibromyalgia (5 papers, 2007 to 2024). A chronic disorder of unknown etiology characterized by pain, stiffness, and tenderness in the muscles of neck, shoulders, back, hips, arms, and legs. "MCP1 elevation was reported in fibromyalgia and linked to insulin signaling impairment in skeletal muscle cells of these patients." (PMID 38650940, 2024). "Additionally, recent studies in humans have identified a link between mitochondrial dysfunction and INS sensitivity in conditions like fibromyalgia (FM), indicating that similar INS and mitochondrial impairments could be underlying factors in various MS and metabolic disorders." (PMID 39595105, 2024).
Gaucher disease (5 papers, 2010 to 2025). Gaucher disease (GD) is a lysosomal storage disorder encompassing three main forms (types 1, 2 and 3), a fetal form and a variant with cardiac involvement (Gaucher disease - ophthalmoplegia - cardiovascular calcification or Gaucher-like disease). "For example, lipid rafts are necessary for correct insulin signalling, and a perturbed lipid raft composition impairs insulin signalling leading to the insulin-resistance observed in patients with Gaucher disease." (PMID 22400113, 2012).
growth deficiency (5 papers, 2021 to 2026). "In prior studies, it has been shown that children with CP who have a growth deficiency have low levels of growth hormone (GH) and Insulin Growth Factor-1 (IGF-1) and are insufficiently responsive to insulin stimulation." (PMID 39201827, 2024). "Experimentally induced intrauterine growth retardation in rats resulted in alterations of the endocrine pancreas, reduced pancreatic weight and β cell mass at birth, and lower insulin secretion in adult life." (PMID 34944170, 2021). "We report a 14-year-old male patient with T1D managed with multiple daily insulin injections who presented with growth failure and delayed puberty in the setting of several years of HbA1c > 12% (SI: > 108 mmol/mol) (reference range, < 5.7% [SI: < 39 mmol/mol])." (PMID 41560719, 2026). "Previous studies have shown that children with CP with growth failure had low basal growth hormone (GH) and Insulin Growth Factor-1 (IGF-1) and responded inadequately to the insulin stimulation test." (PMID 35115566, 2022).
hemorrhagic stroke (5 papers, 2012 to 2021). A stroke caused by a bleed on the brain. "Ang II is also known to inhibit the PI3K/AKT signaling pathway, which regulates the secretion of insulin, leading to lowered insulin sensitivity, which is another risk factor for hemorrhagic stroke." (PMID 33708378, 2021).
hepatoblastoma (5 papers, 2011 to 2017). Hepatoblastoma (HB) is a malignant hepatic tumor and is the most common pediatric liver cancer. "Interestingly, the Beckwith–Wiedemann syndrome, with known elevations of insulin and IGFs during the first years of life, is associated with very high incidence of cancer in childhood, especially hepatoblastoma and Wilm’s tumor." (PMID 26250516, 2015). "In our analysis, the signaling pathways related to liver development that may be disturbed by methylation changes in hepatoblastomas were Metabolism, Cancer, Insulin, MAPK and Wnt signaling pathways, as well as Regulation of the actin cytoskeleton and Adherents junction." (PMID 29228658, 2017). "In addition, in vitro studies have demonstrated an inhibitory effect of insulin and insulin-like growth factor-1 on CBG mRNA expression in a human hepatoblastoma derived Hep G2 cell-line." (PMID 21750736, 2011).
hidradenitis suppurativa (5 papers, 2015 to 2025). A chronic suppurative and cicatricial disease of the apocrine glands occurring chiefly in the axillae in women and in the groin and anal regions in men. "Chronic inflammation in hidradenitis suppurativa (HS) is linked to significant insulin–glucose dysregulation, particularly in patients with a higher degree of inflammation." (PMID 40217596, 2025). "This study aimed to evaluate serum irisin, plasma glucose, insulin, and lipid levels in hidradenitis suppurativa, and elucidate possible associations with disease activity, inflammatory, or metabolic parameters." (PMID 33008659, 2020). "Roflumilast, like apremilast, may induce weight loss, which may improve metabolic profiles and reduce insulin resistance, making it an ideal option for overweight patients with skin conditions, such as those with hidradenitis suppurativa." (PMID 39861739, 2025). "This study indicates that hidradenitis suppurativa patients have higher serum irisin, fasting plasma glucose, insulin, and triglycerides levels than healthy controls." (PMID 33008659, 2020). "Furthermore, plasma triglycerids, glucose, and insulin levels were significantly higher in the hidradenitis suppurativa (p = 0.013, p = 0.001, and p = 0.004), respectively." (PMID 33008659, 2020).
hyperferritinemia (5 papers, 2016 to 2025). "In this regard, hyperferritinemia can lead to reduced insulin secretion and provoke β-cell ferroptosis, a novel mechanism of cell death that is induced by iron overload." (PMID 41283478, 2025). "Additionally, experimental models suggest that insulin induces ferritin synthesis at the mRNA level, providing a potential explanation for the hyperferritinemia frequently observed in the context of IR." (PMID 41283478, 2025). "Iron depletion by phlebotomy enhances insulin sensitivity in patients with NAFLD and hyperferritinemia, according to a case–control study." (PMID 38124275, 2024). "Conventional cardio-metabolic parameters (glucose, HbA1c, total cholesterol, triglycerides, LDL-cholesterol, insulin, HOMA-IR, and hsCRP) were adversely affected in subjects with hyperferritinemia compared with subjects with normal ferritin." (PMID 32240239, 2020). "Hyperferritinemia and mild increased iron stores are frequently observed in patients with NAFLD and several mechanisms have been proposed to explain the role of iron, through oxidative stress and interaction with insulin metabolism, in the development of vascular damage." (PMID 27164079, 2016).
hypovitaminosis (5 papers, 2015 to 2025). "Vitamin D replacement in IGT and DM patients with vitamin deficiencies leads to better insulin secretion, glucose tolerance, and HbA1c." (PMID 41517402, 2025). "This hypothesis was supported by various experimental and clinical studies which showed an enhanced insulin resistance and/or an impaired secretion of insulin in the pancreatic beta cells in the presence of hypovitaminosis D." (PMID 26000307, 2015). "T2DM patients with hypovitaminosis displayed significant differences regarding FBG (P=0.0001), serum insulin (P=0.01), and HOMA-IR (P=0.001) compared to those with sufficient D levels but not for the HbA1c level (0.3)." (PMID 36193546, 2022).
intestinal tumor (5 papers, 2018 to 2024). "In addition to serving as a carrier for retinol, STRA6 also acts as a cell surface signaling receptor for RBP4, influencing the occurrence of intestinal tumors and insulin secretion in pancreatic beta cells." (PMID 39518840, 2024). "These were consistent with qPCR data showing that eif4ebp1 expression, a marker for reduced insulin signaling, was not affected by the intestinal tumor." (PMID 29592890, 2018).
long QT syndrome (5 papers, 2011 to 2022). "A study involving 14 patients diagnosed with KCNQ1 long QT syndrome showed increased postprandial insulin release in KCNQ1 mutation carriers compared with two control participants." (PMID 29259974, 2017). "Variants of the pore-forming alpha-subunit potassium channel gene KCNQ1 are associated with reduced insulin secretion and T2D, and with forms of the long QT-syndrome." (PMID 21291537, 2011). "Kv7.1 is located in both cardiomyocytes and pancreatic β-cells, and it was hypothesized that patients with KCNQ1 long QT syndrome may exhibit increased insulin secretion." (PMID 29259974, 2017).
Mauriac syndrome (5 papers, 2022 to 2026). A complication of poorly controlled type 1 diabetes mellitus in children characterized by linear growth impairment, glycogenic hepatopathy, and Cushingoid features. "Automated insulin delivery is associated with improved glycemic control and psychosocial functioning and can be a safe and effective treatment option for Mauriac syndrome." (PMID 41560719, 2026). "With the improvements in self-monitored blood glucose and insulin, Mauriac syndrome has become increasingly rare." (PMID 39156415, 2024). "Severe growth retardation with pubertal delay, like in Mauriac syndrome, has been reported in patients with T1DM but this syndrome is now uncommon due to improvements in types of insulin therapy, as well as modes of insulin delivery and glycemic control." (PMID 38724932, 2024).
monoclonal gammopathy (5 papers, 2015 to 2025). A condition characterized by the abnormal presence of monoclonal immunoglobulins in the blood or urine. "The signs and symptoms of both monoclonal gammopathy with an anti-insulin monoclonal immunoglobulin and insulin autoimmune syndrome are indistinguishable." (PMID 26241232, 2015). "The cases of monoclonal gammopathy acting as an insulin autoantibody coincide with low-affinity binding, but the monoclonal antibody has a high capacity for binding insulin." (PMID 26241232, 2015). "The relationship between patients with the insulin autoimmune syndrome and a presumptive monoclonal antibody to insulin and those with monoclonal gammopathy and an immunoglobulin that has an affinity for insulin, if any, is not known to us." (PMID 26241232, 2015). "The monoclonal anti-insulin response in persons who develop insulin autoimmune syndrome has not been linked with monoclonal gammopathy." (PMID 26241232, 2015).
mucormycosis (5 papers, 2014 to 2025). "Once the patient was diagnosed with mucormycosis, we started to control DM with insulin, along with amphotericin B which is the first-line antifungal for mucormycosis." (PMID 39618758, 2024).